TOX2 (TOX high mobility group box family member 2)
Description:
Putative transcriptional activator involved in the hypothalamo-pituitary-gonadal system.
Synonyms: GCX-1; C20orf100; GCX1; dJ1108D11.2; dJ495O3.1
Tractability: PROTAC: ubiquitination databases record sites on it.
Gene: Protein-coding gene on chromosome 20 (43,914,844 to 44,069,616, forward strand). Ensembl gene ENSG00000124191.
Subcellular location: Nucleus
Subcellular location (Human Protein Atlas): Nucleoplasm
Gene Ontology:
Molecular function: transcription coactivator activity; chromatin DNA binding
Biological process: positive regulation of transcription by RNA polymerase II; regulation of transcription by RNA polymerase II
Cellular component: nucleoplasm; nucleus
Genetic constraint (gnomAD): Loss-of-function variants: 15 observed, 45.73 expected, observed/expected ratio (o/e) 0.33, 90% interval 0.22 to 0.5. The upper end of that interval is the gene's LOEUF score, 0.5, which puts it in group 2 of 6, group 1 being the genes least tolerant of losing a copy. Missense variants: 621 observed, 673.39 expected, observed/expected ratio (o/e) 0.92, 90% interval 0.86 to 0.99. Synonymous variants: 289 observed, 287.57 expected, observed/expected ratio (o/e) 1, 90% interval 0.91 to 1.11.
Homologues: Orthologues: chimpanzee TOX2 (99% identical), pig TOX2 (94% identical), mouse Tox2 (92% identical), guinea pig TOX2 (91% identical), dog TOX2 (90% identical), rabbit TOX2 (87% identical), rat Tox2 (87% identical), macaque TOX2 (84% identical), tropical clawed frog tox2 (67% identical), zebrafish tox2 (46% identical), Caenorhabditis elegans hmg-4 (10% identical), Caenorhabditis elegans hmg-3 (9% identical). Paralogues in human: TOX (46% identical), TOX3 (38% identical), TOX4 (32% identical), HMGXB4 (18% identical), UBTF (15% identical), SP100 (15% identical), SMARCE1 (14% identical), SSRP1 (12% identical), HMGB2 (11% identical), HMGB1 (11% identical), HMGB1P1 (11% identical), SP140 (11% identical), and 8 more.
Diseases named in the same sentence as TOX2 in open-access papers:
TOX2 is named in the same sentence as 32 diseases in open-access papers, as found by Europe PMC text mining. Sharing a sentence is not in itself a finding about the gene and the disease. The quoted sentences say what the papers report.
colorectal cancer (4 papers, 2022 to 2024). A primary or metastatic malignant neoplasm that affects the colon or rectum. "TOX2 upregulation is associated with decreased overall survival in NK/T-cell lymphomas and progression of colorectal cancer, which contrasts with the signature-predicted effect for neuroblastoma." (PMID 38398114, 2024). "It is well known that transcription activation of immune checkpoints can be effectively induced by histone modification, and H3K4me3 enrichment contributes to PD-L1 and TOX2 expression in colorectal cancer." (PMID 39201460, 2024).
lung carcinoma (3 papers, 2012 to 2018). "Our data show that TOX2 is expressed in human lungs and epigenetic inactivation of this gene in lung cancer modulates multiple pathways." (PMID 22496870, 2012). "The prevalence for methylation of TOX2 in lung cancer was similar between adenocarcinoma and squamous cell carcinoma." (PMID 22496870, 2012). "TOX2 was also found to be hypermethylated and consequently downregulated in breast and lung cancer." (PMID 29568396, 2018). "In HBEC and the lung cancer cell lines H1299 and SKLU1 with unmethylated TOX2 promoter CpG island, both TOX2 transcripts were expressed at levels similar to DNLT." (PMID 22496870, 2012). "TOX high mobility group box family member 2 (TOX2) is not methylated in normal lung cancer cells." (PMID 29796116, 2018). "Although these knockdowns did not result in further phenotypic changes of lung cancer cells in vitro, the impact on tissue remodeling, inflammatory response, and cell differentiation pathways suggest a potential role for TOX2 in modulating tumor microenvironment." (PMID 22496870, 2012). "In this regard, the differential methylation of TOX and TOX3 between lung and breast cancer, TOX2 across cigarette smoking habit, and TOX3 by the histology of lung cancer suggest, methylation of TOX subfamily genes could be important biomarkers for cancer profiling." (PMID 22496870, 2012).
virus infection (3 papers, 2020 to 2024). "As summarized in this review, Tfh cell-related transcription factors including Bcl6, IRF4, STAT1/STAT4/STAT5, T-bet, TCF-1, LEF-1, TOX2, Bach2, FOXP1, and KLF2 are all involved in the virus infection." (PMID 32766317, 2020). "Collectively, our data highlight the overlap of key significant genes such as DGKA (NK and T-cell viral infection), EGR2 (T-cell viral infection and CD8 T-cell exhaustion), and the potential role of key TFs including EGR2, NFAT2 (NFATc1), and TOX2 in driving NK cell anergy." (PMID 38637625, 2024).
acute myeloid leukemia (2 papers, 2023 to 2024). Acute myeloid leukemia (AML) is a group of neoplasms arising from precursor cells committed to the myeloid cell-line differentiation. "TOX2 has been related to the survival of patients with acute myeloid leukemia and the pathogenesis of atopic dermatitis." (PMID 39766129, 2024). "TOX2 was recently reported to be a novel tumor driver in natural killer/T-cell lymphoma (NKTL) and high expression of TOX2 was associated with worse overall survival in both NKTL and acute myeloid leukemia (AML)." (PMID 36417130, 2023).
glioma (2 papers, 2018 to 2020). A benign or malignant brain and spinal cord tumor that arises from glial cells (astrocytes, oligodendrocytes, ependymal cells). "More interestingly, we identified TOX2 as a promising tumor biomarker, suggesting its possible role in gliomas development, with a differential expression in PAs with different brain localization and a more pronounced hypermethylation in glioblastomas." (PMID 29568396, 2018). "The in silico analysis of these high grade gliomas also allowed us to point out that TOX2 hypermethylation in glioblastomas seems to be independent from tumor localization and is present in both pediatric and adult age." (PMID 29568396, 2018). "Furthermore, by analyzing in silico methylation data from glioblastomas (GSE19391), we have been able to confirm that the methylation alteration near TOX2 gene is also present in high grade gliomas." (PMID 29568396, 2018). "The analysis of TOX protein family members showed coexpression of TOX, TOX2, TOX3, and TOX4 in pan-glioma analysis, LGG alone, and GBM alone." (PMID 32762688, 2020).
T Cell Lymphoma (2 papers, 2023). "TOX2 is a novel tumor driver, which promotes in Natural Killer/T-Cell Lymphoma cell growth and enhances ability of colony formation, as well as protects cell viability under adverse condition." (PMID 36417130, 2023).
T-cell acute lymphoblastic leukemia (2 papers, 2024 to 2025). Acute lymphoblastic leukemia of T-cell origin. "We observed that tumor samples from T-cell acute lymphoblastic leukemia (T-ALL) patients and some T-ALL cell lines had high TOX and TOX2 expression together with a low level of TIM3 expression, contradicting previous reports that TOX and TOX2 upregulate TIM3 expression in tumor-specific T cells." (PMID 39080376, 2024).
acute lymphoblastic leukemia (1 paper, 2024). Leukemia with an acute onset, characterized by the presence of lymphoblasts in the bone marrow and the peripheral blood. "Here, we demonstrate two distinct TIM3 expression patterns (high & low) with high TOX and TOX2 levels in T-cell acute lymphoblastic leukemia (T-ALL) specimens and cell lines." (PMID 39080376, 2024).
breast carcinoma (1 paper, 2012). "Further studies focused on characterizing TOX2, a gene whose promoter CpG island was found to be specifically methylated in lung and breast cancer." (PMID 22496870, 2012). "The presence and degree of methylation within TOX2 promoter CpG island was first screened in lung and breast cancer cell lines using COBRA." (PMID 22496870, 2012). "Dense methylation of the TOX2 promoter silenced both of these transcripts in lung and breast cancer cells and DAC treatment restored expression of both transcripts in vitro confirming epigenetic regulation." (PMID 22496870, 2012).
breast tumors (1 paper, 2012). "Extension of these assays to other members of TOX subfamily genes that share similar genomic structure and protein homology to TOX2 revealed distinct methylation profiles between lung and breast tumors." (PMID 22496870, 2012). "Among primary tumors, TOX2 methylation was detected in 28% (54/190) lung and 23% (18/80) breast tumors." (PMID 22496870, 2012). "These similarities and the discovery of aberrant methylation of TOX2 in lung and breast tumors prompted us to evaluate the methylation status of the remaining TOX subfamily genes." (PMID 22496870, 2012).
depression (1 paper, 2017). "TOX2 is a putative transcriptional activator involved in the hypothalamo–pituitary–gonadal system and is located in a large genomic region that has been previously reported as associated with depression symptoms in psychotic illness." (PMID 28153336, 2017).
inflammatory bowel disease (1 paper, 2024). A spectrum of small and large bowel inflammatory diseases of unknown etiology. "TOX2 (TOX high mobility group box family member 2) is a transcription factor related to T cell exhaustion, which is a broad term used to describe the T cell functions in conditions of chronic antigen stimulation, such as inflammatory bowel disease and response to tumors." (PMID 39766129, 2024).
influenza (1 paper, 2021). An acute viral infection of the respiratory tract, occurring in isolated cases, in epidemics, or in pandemics; it is caused by serologically different strains of viruses (influenzaviruses) designated A, B, and C, has a 3-day incubation period, and usually lasts for 3 to 10 days. "Collectively, both primary and secondary TFH responses after influenza infection were diminished in Tox2-deficient mice." (PMID 34623911, 2021). "Consistent with the immune responses following SRBC immunization, induction of secondary response of influenza virus by PR8 infection decreased GC TFH cells in the spleens at day 5 after infection of Tox2-deficient mice as compared to WT mice." (PMID 34623911, 2021). "Thus, impaired TFH cell phenotype in influenza-infected Tox2-deficient mice did not largely affect Ab responses following influenza virus infection, probably because the primary mechanism for Ab production in influenza virus infection is via an extrafollicular pathway." (PMID 34623911, 2021).
lung adenocarcinoma (1 paper, 2012). A carcinoma that arises from the lung and is characterized by the presence of malignant glandular epithelial cells. "Interestingly, TOX2 methylation among lung adenocarcinoma patients was significantly more prevalent in tumors from current smokers 43% (16/37) compared to never smokers 24% (18/75) or current non-smokers (former and never smokers combined) 26% (35/134) (p<0.05)." (PMID 22496870, 2012). "Although not statistically significant, TOX2 methylation in lung adenocarcinoma from current smokers was also higher than former smokers (43% vs. 29%, p = 0.15)." (PMID 22496870, 2012).
nasopharyngeal carcinoma (1 paper, 2024). A carcinoma arising from the nasopharyngeal epithelium. "We found a mutual positive association between TOX and TOX2, TOX and HAVCR2, and TOX2 and HAVCR2 at the transcriptional level in CD3+ tumor-infiltrating T cells (TILs) in single cell (sc)RNA-sequencing of nasopharyngeal carcinoma samples." (PMID 39080376, 2024).
ulcerative colitis (1 paper, 2024). An inflammatory bowel disease involving the mucosal surface of the large intestine and rectum. "In conclusion, the network classified the three diagnoses with high performance, and LAIR1 and TOX2 were found to correlate with the severity of ulcerative colitis." (PMID 39766129, 2024). "Explainable artificial intelligence for computer vision was used with the Grad-CAM technique, and additional LAIR1 and TOX2 immunohistochemistry was performed in ulcerative colitis to analyze the immune microenvironment." (PMID 39766129, 2024). "Due to its relationship with PD-1, TOX2 is a promising immuno-oncology marker in ulcerative colitis as well." (PMID 39766129, 2024). "LAIR1 and TOX2 have emerged as two promising immuno-oncology markers for ulcerative colitis." (PMID 39766129, 2024). "Finally, LAIR1 and TOX2 expressions were analyzed in the ulcerative colitis cases." (PMID 39766129, 2024). "The CNNs also differentiated between steroid-requiring and mesalazine-responsive ulcerative colitis based on H&E, LAIR1, and TOX2 staining." (PMID 39766129, 2024).
tumor (34 papers, 2012 to 2026). "Accordingly, the murine model has shown that CAR T deficient for tox1 and tox2 are more effective than wild-type CARs in suppressing tumor growth." (PMID 35406703, 2022). "Interestingly, CAR TILs deficient in both TOX and TOX2 showed increased effector functions and prolonged survival of tumor-bearing mice, and their exhausted features were obviously attenuated." (PMID 36761757, 2023). "Additionally, CAR T cells deficient in both Tox and Tox2 were more effective than WT in augmenting effector cytokine expression, reducing inhibitory receptor expression, controlling tumor growth and extending survival of tumor-bearing mice." (PMID 34548096, 2021). "One study reported that both TOX and TOX2-deficient CAR-T were able to suppress tumor growth and prolong survival of tumor-bearing mice." (PMID 41502492, 2026). "Increased expression of TOX2 can influence the growth, survival, ability to form colonies, and prognosis of tumor cells." (PMID 39838405, 2025). "Intriguingly, compared with single KOs, the double KO of TOX and TOX2 achieved superior tumor control." (PMID 40693464, 2025). "Among these genes, IRF8 and TOX2 encode for transcription factors involved in immune cell regulation and development, with IRF8 playing a tumor suppressor role in AML and TOX2 being involved in regulation of T-cell response in CLL." (PMID 40456839, 2025). "Double-deficient CAR-tumor-infiltrating lymphocytes (TILs) of TOX and TOX2 showed increased cytokine expression and decreased inhibitory receptor expression, and more efficiently prevented tumor growth than wild-type CAR-T cells." (PMID 38918817, 2024). "TOX and TOX2 have been reported to induce tumor-specific T-cell exhaustion with upregulation of checkpoint proteins, such as TIM3 and PD-1." (PMID 39080376, 2024). "While the Tumor_2 had relative mild cancer hallmark signatures but expressed genes associated with tumor survival signal and drug resistance (IL32, TOX2, AIF1, AKAP12, CD38 etc.), and eventually became the main tumor subtype post-treatment." (PMID 36417130, 2023). "For example, downregulated histone 3 lysine 9 trimethylation and upregulated histone 3 lysine 4 trimethylation are observed in the promoters of PD-L1 and TOX2 in CRC tumor tissues." (PMID 37180158, 2023). "Disruption the expression and activity of TOX and TOX2 in CAR T cells promoted tumor regression in tumor-bearing mouse models." (PMID 36568989, 2022). "The tumor-specific B cell subpopulation B7 has 855 specific genes (the common genes are removed) and the gene with the highest fold-change is TOX2." (PMID 34362918, 2021). "TOX and TOX2 induced T cell exhaustion in different tumor mouse models and cancer patients as well as in patient hematological malignancies." (PMID 33743809, 2021). "Network analysis shows that target genes of TOX2 are remarkably highly enriched (4.5-fold, p-value 2.83E−09) in tumor-specific genes." (PMID 34362918, 2021). "We examined the cis-elements near the TOX2 gene in scATAC-seq data and identified four cis-elements that are specifically open in tumor-specific B cell subpopulations." (PMID 34362918, 2021). "In agreement with our findings, Tox and Tox2 were upregulated in exhausted PD-1highTIM3high tumor-infiltrating CD8+ T cells expressing chimeric antigen receptors (CAR)." (PMID 34548096, 2021). "TOX and TOX2 deficient CAR+ TILs can prevent tumor growth and prolong survival of tumor-bearing mice." (PMID 32117960, 2020). "IRX2 and TOX2 gene expression levels in tumor samples were compared to commercially available human normal brain samples and to GTEx expression data observed in different normal brain sites." (PMID 29568396, 2018). "Here we reported that zanubrutinib overcame TOX2+ terminal Tex cells during both immune‐bridging and immune‐maintenance therapy, correlating with reduced abundance of tumour‐infiltrating PD‐1‐overexpressing terminal Tex cells and good response to CAR T‐cell therapy." (PMID 40268516, 2025).